RAC1 (Rac family small GTPase 1)
Diseases named in the same sentence as RAC1 in open-access papers (continued):
Sharing a sentence is not in itself a finding about the gene and the disease.
papilloma (8 papers, 2011 to 2021). A benign epithelial neoplasm that projects above the surrounding epithelial surface and consists of villous or arborescent outgrowths of fibrovascular stroma. "RAC1 inhibition suppresses HPV8-associated papilloma formation in mice, while RAC1 activation facilitates papillomatosis." (PMID 34439095, 2021). "Genetically removing one Rac1 allele significantly impaired K-Ras induced oral papilloma growth and promoted survival while reducing levels of active Rac1 within the papillomas." (PMID 21358804, 2011). "Interestingly, only 3 out of 20 (15%) K14 HPV-8 transgenic mice with epidermis specific expression of only one Rac1 allele (K14 HPV-8/Rac1-EKOhet) developed skin papillomas starting from P126, suggesting a dose effect of Rac1 expression on papilloma formation." (PMID 27506937, 2016). "This shows that Rac1 activity essentially supports HPV-8 induced papilloma formation in skin but cannot induce papillomas by itself." (PMID 27506937, 2016). "Our data show that inhibition or deletion of Rac1 results in reduced papilloma formation upon UV-irradiation with a single dose, whereas constitutive activation of Rac1 strongly increases papilloma frequency in these mice." (PMID 27506937, 2016). "Quantification of γH2AX positive nuclei showed that papillomas in K14 HPV-8 mice (n = 3) contain about 3 times as many positive nuclei compared to SCCs of K14 HPV-8/Rac1-EKO mice (n = 4)." (PMID 27506937, 2016). "Targeted deletion of Rac1 or inhibition of Rac1 activity in epidermal keratinocytes reduced papilloma formation in a chemical skin carcinogenesis mouse model." (PMID 27506937, 2016). "Cell culture systems of primary papilloma cells have allowed the identification of candidate therapeutic targets such as Rac1, high-throughput drug screening, and the successful application of personalized medicine approaches to treat a lung malignancy resulting from RRP progression." (PMID 33418959, 2021). "We show that, on one hand and in agreement with previous studies, inhibition or deletion of Rac1 results in a reduced number of spontaneous or UV-light induced papillomas in K14 HPV-8 mice, whereas constitutive activation of Rac1 facilitates papilloma formation in these mice." (PMID 27506937, 2016). "In agreement with the described role of Tiam1, one function of Rac1 may be to transmit growth factor signals from the tumor environment which stimulate papilloma growth." (PMID 27506937, 2016). "Interestingly, loss of one Rac1 allele did not reduce Rac1 activation within papillomas by 50%, consistent with the requirement for a threshold level of Rac1 activation for papillomagenesis." (PMID 21358804, 2011). "Rac1 can facilitate papilloma formation in HPV negative 8 transgenic mice and is active in HPV-mediated respiratory papillomatosis." (PMID 31226168, 2019). "Upon inhibition or in the absence of Rac1, such signals could be ameliorated, which results in a lower number of clinically apparent papillomas." (PMID 27506937, 2016). "In contrast, none of the 15 K14 HPV-8/Rac1-EKO mice developed papillomas." (PMID 27506937, 2016). "Our stainings of γH2AX show multiple positive foci in papillomas of K14 HPV-8 mice, but not in SCCs of K14 HPV-8/Rac1-EKO mice)." (PMID 27506937, 2016). "A similar mechanism could explain why, upon constitutive activation of Rac1, K14 HPV-8/K14 L61Rac1 mice develop papillomas, but not carcinomas: in these mice Rac1 dependent mechanisms controlling senescence are still functioning." (PMID 27506937, 2016). "On the other hand, constitutive activation of Rac1, in addition to expression of HPV-8, led to the development of papillomas, but not SCCs, in 100% of the double transgenic K14 HPV-8/K14 L61Rac1 mice, whereas K14 L61Rac1 mice without HPV-8 did not develop skin papillomas." (PMID 27506937, 2016).
renal cell carcinoma (8 papers, 2020 to 2024). "The analysis and detection of renal cell carcinoma(RCC) samples showed that Rac1 protein was highly expressed, which was positively correlated with the poor clinical prognosis of RCC." (PMID 34079763, 2021).
cholangiocarcinoma (7 papers, 2016 to 2022). A carcinoma that arises from the intrahepatic biliary tree (intrahepatic cholangiocarcinoma) or from the junction, or adjacent to the junction, of the right and left hepatic ducts (hilar cholangiocarcinoma). "Our previous work showed that β6 induced the expression of MMP9 and promoted the invasiveness of cholangiocarcinoma cells in a Rac1-dependent manner." (PMID 27440504, 2016). "By targeting and activating Rac1, β6 promotes the development and progression of cholangiocarcinoma." (PMID 27440504, 2016). "In addition, we found that β6 silencing significantly decreased Rac1-GTPase activity, while β6 overexpression increased Rac1 activity in cholangiocarcinoma cells." (PMID 27440504, 2016). "Integrin β6 promoted the migratory and invasive capacities of cholangiocarcinoma cells by activating Rac1, indicating that integrin β6 may be a potential target for the treatment of cholangiocarcinoma." (PMID 27440504, 2016). "Therefore, targeting Rac1 may be a promising therapeutic approach for the treatment of cholangiocarcinoma." (PMID 27440504, 2016). "Moreover, integrin β6 promotes the development of cholangiocarcinoma by activating Rac1." (PMID 27440504, 2016). "First, using the specific Rac1 activity inhibitor NSC23766, we found that Rac1 was essential for the migration and invasion of cholangiocarcinoma cells, as NSC23766 suppressed migration and invasion of RBE cells in a dose-dependent manner." (PMID 27440504, 2016).
developmental delay (7 papers, 2022 to 2024). "A recent, uncharacterized point mutation (DDD4K.02292) 4729G > A, within the Rac1-GEF domain of Kalirin was found in an individual with severe developmental delay." (PMID 36533124, 2022). "De novo RAC1 missense variants have been identified in neurodevelopmental disorders with global developmental delay/ID and brain size abnormalities as core phenotypes (Mental Retardation autosomal dominant 48, MRD48, OMIM #617751)." (PMID 35203342, 2022). "Pathogenic RAC1 variants result in developmental delay and multiple anomalies." (PMID 37328543, 2023). "Here we show that a single point mutation within the Rac1-GEF PH domain of KALRN, found in a patient with developmental delay, results in loss of catalytic activity." (PMID 36533124, 2022). "Together these results indicate that reduced Rac1-GEF activity as result of E1577K mutation impairs neuroarchitecture, connectivity and NMDAr activity, and is a likely contributor to impaired neurodevelopment in a patient with developmental delay." (PMID 36533124, 2022). "Thus, loss of Rac1-GEF activity is impairs the ability of Kalirin-7 to drive NMDAr surface expression and activity, likely contributing to the patient’s observed developmental delay." (PMID 36533124, 2022).
focal segmental glomerulosclerosis (7 papers, 2017 to 2025). A renal disorder characterized by sclerotic lesions in the glomeruli. "For examples, Q158R mutation of ArhGAP24 (FilGAP) found in focal segmental glomerulosclerosis causes loss of Rac1-GAP activity." (PMID 40632829, 2025). "Studies showed Rac1-activating mutations are responsible for inherited cases of focal segmental glomerulosclerosis, leading to the stimulation of TRPC5 ion channel activity and cytoskeletal remodeling in podocytes." (PMID 38384797, 2024). "Another small G protein that may be a novel target for TRPC5, Rac1, is known to mediate podocyte injury in focal segmental glomerulosclerosis." (PMID 38384797, 2024). "For example, human gene mutations in Rac1 regulatory proteins, ARHGAP24 and ARGHDIA, have been reported to alter Rac1 activity and are associated with focal segmental glomerulosclerosis; more so, recent evidence suggests that these disturbances are implicated in minimal change disease." (PMID 28880939, 2017). "For instance, the Rac1-GAP ARHGAP24 knock-down in podocytes increased membrane ruffling, while a loss-of-function mutation in the ARHGAP24 gene was associated with hereditary focal segmental glomerulosclerosis (FSGS), a kidney disease characterized by podocyte dysfunction." (PMID 41306285, 2025).
myocardial infarction (7 papers, 2014 to 2025). Gross necrosis of the myocardium, as a result of interruption of the blood supply to the area, as in coronary thrombosis. "In myocardial infarction, the RAC1 protein in the brain cortex tissue paired with the BioCarta AT1R pathway was enriched." (PMID 34805976, 2021). "In terms of myocardial infarction, the RAC1 protein serves as a small GTP-binding protein that regulates NADPH oxidase." (PMID 34805976, 2021). "They showed that in the heritable hyperlipidemic rabbits, which are prone to the myocardial infarction, the level of unmodified RhoA and Rac1 and the levels of a membrane-bound (geranylgeranylated) RhoA and Rac1 increased with age (assessed between 3 and 7 months)." (PMID 33379334, 2020). "Elevated expression levels of RAC1, IQGAP1, MYL6, DBN1, SLC2A1 and SLC2A3 were observed in acute myocardial infarction patients compared to healthy controls, suggesting a strong association with disease progression and indicating their potential as novel therapeutic targets." (PMID 40672380, 2025).
Obesity (7 papers, 2017 to 2025). Accumulation of substantial excess body fat. "Therefore, Rho GTPases and Rac1 could serve as critical mediators linking the metabolic dysfunction caused by obesity and systemic insulin resistance with the increased metastatic potential of TNBC​." (PMID 40629272, 2025). "This understanding positions Rac1 as a promising therapeutic target, particularly in patients with obesity-related metabolic comorbidities, providing a rationale for further exploration of Rac1 inhibition in mitigating metastatic burden​." (PMID 40629272, 2025). "RAC1 was characterised by the presence of obesity, and upregulation of the complement pathway and leptin signalling." (PMID 39401856, 2024). "Further studies are needed to determine the target of obesity-induced negative regulation downstream of Rac1." (PMID 37511290, 2023). "The effect of obesity on signal transduction downstream of Rac1 for the induction of GLUT4 translocation was then investigated." (PMID 37511290, 2023). "RAC1 is expressed in insulin-sensitive tissues, including AT and skeletal muscle, while activated RAC1 induces oxidative stress in β-cells in obesity." (PMID 35885044, 2022). "This Src–Vav–RAC1–MLK pathway is required for obesity in mice as data have shown that mice with JIP, Vav, and MLK deficiency were protected from obesity after HFD feeding." (PMID 31270248, 2019). "In this study, we investigated whether Rac1-mediated signaling that regulates glucose uptake in skeletal muscle was affected by obesity by employing the Lepob/ob mouse model." (PMID 37511290, 2023). "Moreover, it is important to clarify the mechanisms whereby signal transduction cascades upstream and downstream of Rac1 are affected by obesity." (PMID 37511290, 2023). "Therefore, we herein employed the leptin-deficient obese (Lepob/ob) mouse model and assessed the effects of obesity on Rac1-mediated insulin signaling in skeletal muscle." (PMID 37511290, 2023). "Hence, it is plausible that mechanisms whereby Akt2 causes the activation of Rac1 are not affected by obesity." (PMID 37511290, 2023). "Additionally, we showed that signal transduction for the regulation of RalA downstream of Rac1 was partially impaired in Lepob/ob mice, whereas signaling downstream of RalA that led to GLUT4 translocation was unaffected by obesity." (PMID 37511290, 2023). "Contraction-stimulated, AMPK-independent mechanisms for Rac1 activation may also be different from those in insulin signaling and may not be inhibited by obesity." (PMID 37511290, 2023). "Collectively, signal transduction for the regulation of RalA downstream of Rac1 was partially inhibited in Lepob/ob mice, whereas the regulation of GLUT4 translocation downstream of RalA was not affected by obesity." (PMID 37511290, 2023). "Whether integrins and the IPP complex directly regulate Rac1 or cofilin in obesity is not yet known, nor is it known what role the IPP complex may play in obesity through its other binding partners." (PMID 29043068, 2017). "It is plausible that the activity of Rac1 is regulated downstream of AMPK by mechanisms other than those in insulin signaling involving Akt2, and therefore, Rac1 activation downstream of AMPK may not be impaired by obesity." (PMID 37511290, 2023).
pulmonary fibrosis (7 papers, 2015 to 2025). Chronic progressive interstitial lung disorder characterized by the replacement of the lung tissue by connective tissue, leading to progressive dyspnea, respiratory failure, or right heart failure. "Activation of Rac1 by geranylgeranylation in alveolar macrophages promotes characteristics of M2 macrophages and associates with the development of oxidative stress and pulmonary fibrosis." (PMID 26962470, 2015). "While statins promoted pulmonary fibrosis via Rac1 activation in macrophages, deletion of Rac1 has a protective effect." (PMID 37681924, 2023). "A critical regulatory role for Rac1 in the onset of pulmonary fibrosis is considered due to increased H2O2 production in alveolar macrophages, and Cys-189 of Rac1 is necessary for its mitochondrial import." (PMID 31277234, 2019). "Digeranyl bisphosphonate (DGBP), which impairs geranylgeranylation of Rho GTPases by inhibiting geranylgeranyl diphosphate synthase, reduces mitochondrial oxidative stress and abrogates progression of pulmonary fibrosis by inhibiting Rac1 activation and its mitochondrial translocation." (PMID 26962470, 2015). "And FPR2 inhibitor reduced Th-IR induced activation of the Rac1/NF-κB pathway in macrophages and further alleviated SAA-induced lung fibrosis." (PMID 39309438, 2024).
Arthritis (6 papers, 2010 to 2024). Inflammation of a joint. "Consistently, inactivating Iqgap1 normalizes Rac1 GTP-loading, and reduces inflammation and arthritis in GGTase-I-deficient mice, as well as prevents statins from increasing Rac1 GTP-loading and cytokine production in macrophages." (PMID 31484924, 2019). "However, mice in which Rac1 has been conditionally deleted in mature neutrophils and macrophages on a Rac2-deficient background show a complex phenotype in a Chlamydia-induced infection model of arthritis." (PMID 20053277, 2010). "Of these RHO GTPases, RHOA and RAC1 regulate synovial fibroblast behavior and arthritis severity and joint damage in autoimmune arthritis." (PMID 39683640, 2024). "Inactivating IQGAP1 normalized Rac1 GTP-loading and reduced inflammation and arthritis in GTPase-I-deficient mice, preventing statins from increasing Rac1 GTP-loading and cytokine production in macrophages." (PMID 38791282, 2024). "Knockout of Iqgap1 normalized Rac1-GTP loading, abolished proinflammatory signaling and cytokine production, and markedly reduced arthritis in GGTase-I-deficient mice." (PMID 31484924, 2019). "Targeting Rac1 using an inhibitory peptide was also shown to reduce paw swelling in early arthritis and to a lesser extent in chronic arthritis in a collagen-induced arthritis murine model." (PMID 27442895, 2017). "We demonstrate that a cell-permeable inhibitory Rac1 carboxy-terminal peptide can reduce paw swelling and antibody production during murine experimental arthritis." (PMID 20053277, 2010). "Here we show that heterozygous deletion of the Rho family gene Rac1, but not Rhoa and Cdc42, reverses inflammation and arthritis in GGTase-I-deficient mice." (PMID 31484924, 2019). "This is clearly demonstrated by the role of Rac1 in arthritis." (PMID 27442895, 2017). "However, only heterozygous deletion of gene Rac1, but not Cdc42 and RhoA, could reverse inflammation in mouse models for arthritis, indicating the special role of Rac1 in chronic inflammation diseases." (PMID 34805177, 2021). "A role for Rac1 in maintaining vascular endothelial integrity in vivo is also indirectly suggested in studies of c-Jun knockout mice, in which inhibition of c-Jun, a downstream target of Rac signaling, suppresses edema, paw swelling, and inflammation in an experimental model of arthritis." (PMID 20053277, 2010). "Whether or not Iqgap1 influences Rac1-GTP signaling and cytokine production in arthritis and other inflammatory diseases in the setting of wild-type GGTase-I remains to be determined." (PMID 31484924, 2019).
astrocytoma (6 papers, 2011 to 2025). "Immunoreactivity for Rac1 in the plasma membrane and/or perinuclear region was also observed in astrocytoma cells with relatively intense cytoplasmic staining and was found to have significant positive association with cytoplasmic Rac1." (PMID 27790861, 2016). "In an astrocytoma cell line, suppression of endogenous FilGAP expression by siRNAs caused an increased proportion of mesenchymal elongated cells, probably through increased Rac1 activity." (PMID 27790861, 2016). "The inhibition of Rho kinase, one of the RhoA effectors, affects astrocytoma morphology, motility, and invasion by activating Rac1." (PMID 41369326, 2025). "The inhibition of Rho kinase affects astrocytoma morphology, motility, and invasion through the activation of Rac1." (PMID 41369326, 2025). "This study clearly provided evidence that cytoplasmic Rac1 immunoreactivity showed a strong grade‐dependent increase in astrocytomas." (PMID 27790861, 2016). "RhoA activation in astrocytoma cells has been demonstrated to confer cell process retraction and rounding in the presence of decreased Rac1 activity." (PMID 24109588, 2013). "We also investigated the effect of δ-catenin on Rac1 activity and the biological behavior of astrocytoma cell lines." (PMID 22151302, 2011). "Overexpression of δ-catenin activated Rac1 and promoted astrocytoma cell proliferation and invasion." (PMID 22151302, 2011). "The results suggest that δ-catenin expression is associated with the malignant progression of astrocytoma and promotes astrocytoma cell invasion through upregulation of Rac1 activity." (PMID 22151302, 2011). "Moreover, Ect2 co-localizes with Rac1 and Cdc42 in the membrane ruffles of migratory astrocytoma cells, and inhibition of Ect2 led to decreased Rac1 and Cdc42 activity, with no change in Rho activity." (PMID 24109588, 2013). "The levels of Rac1 protein correlate with tumor grade in astrocytomas." (PMID 24109588, 2013). "In addition, CTNND2 overexpression promoted proliferation, invasion and Rac1 activity of U251 astrocytoma cells." (PMID 22151302, 2011). "In fact, the OS and PFS of patients with high Rac1 scores appeared to be significantly poorer than those with Rac1‐negative tumors, again indicating that Rac1 activity may contribute to the aggressive feature of astrocytomas." (PMID 27790861, 2016). "Given our results that showed positive correlations among cytoplasmic Rac1, FLNa, and integrin β2, it is likely that FilGAP may serve as a key regulator for modulation of Rac1 activity through its interaction with the FLNa/integrin β2 axis in astrocytoma cells." (PMID 27790861, 2016). "Furthermore, ROCK inhibition increases Rac1 activity in osteoblast and astrocytoma cells." (PMID 24523903, 2014). "In this study, we investigated the expression of FilGAP, with reference to the status of its related molecules, including FLNa, integrin β2, and Rac1, as well as the expression of ECT 2, cell proliferation, and IDH1 gene status in astrocytomas." (PMID 27790861, 2016). "We investigated δ-catenin expression in human astrocytoma samples and its function in astrocytoma cell lines using immunohistochemistry, siRNA knockdown, transfection, MTT, transwell migration and Rac1 pulldown techniques." (PMID 22151302, 2011). "From our results, although both nuclear and cytoplasmic ECT2 expression showed significant grade‐dependent increases in astrocytomas, the nuclear, but not cytoplasmic, ECT2 scores were positively correlated with cytoplasmic Rac1 expression." (PMID 27790861, 2016).